RNU6-590P (RNA, U6 small nuclear 590, pseudogene)
Gene: Small nuclear RNA gene on chromosome 12 (13,459,670 to 13,459,776, reverse strand). Ensembl gene ENSG00000201909.
Homologues: Orthologues: chimpanzee U6 (99% identical), macaque U6 (93% identical), rat LOC120102603 (72% identical), dog U6 (67% identical), guinea pig U6 (60% identical). Paralogues in human: RNU6-15P (87% identical), RNU6-116P (86% identical), RNU6-1331P (86% identical), RNU6-25P (86% identical), RNU6-310P (86% identical), RNU6-378P (86% identical), RNU6-38P (86% identical), RNU6-41P (86% identical), RNU6-43P (86% identical), RNU6-574P (86% identical), RNU6-1 (85% identical), RNU6-1042P (85% identical), and 1285 more.